IGF1 (insulin like growth factor 1)
Diseases named in the same sentence as IGF1 in open-access papers (continued):
Sharing a sentence is not in itself a finding about the gene and the disease.
myocardial ischemia (17 papers, 2011 to 2025). A disorder of cardiac function caused by insufficient blood flow to the muscle tissue of the heart. "In recent years, investigations found that IGF-1 has a protective effect on cardiovascular disease, especially in myocardial ischemia-reperfusion injury." (PMID 26844226, 2015). "Anti-fibrotic and anti-apoptotic properties of IGF-1 have been demonstrated in various models of myocardial ischemia." (PMID 23508361, 2012). "Treatment with IGF-1 in myocardial ischemia rats significantly reduced (p < 0.05) CK-MB and LDH levels when compared with untreated myocardial ischemia rats." (PMID 21651821, 2011). "The present study was aimed to evaluate the effects of IGF-1 on circulating level of angiogenic cytokine interleukin-8 (IL-8), in experimentally-induced myocardial ischemia in rats." (PMID 22272091, 2011). "Another finding in the present study was that the levels of both the biomarkers of cardiac injury, CK-MB and LDH, were significantly attenuated after IGF-1 treatment of rats with induced myocardial ischemia." (PMID 21651821, 2011). "When serum IGF-1 levels were compared among the different experimental groups, we observed that there was a significant increase (p < 0.05), compared with control, in IGF-1 level ten days after commencement of the ISO treatment that led to myocardial ischemia." (PMID 21651821, 2011). "Aim of the present study was to look into the effects of insulin like growth factor -1 (IGF-1) on circulating angiogenic factors after myocardial ischemia in rats." (PMID 21651821, 2011). "A prior study showed that insulin-like growth factor-1 (IGF-1) may protect cardiac tissue against myocardial ischemia/reperfusion (I/R) injury through the PI3K/Akt pathway in rats." (PMID 36788811, 2023). "Meanwhile, some studies have suggested that the function of miR-320 targeting IGF1 was related to angiogenesis in diabetic hearts, myocardial ischemia and reperfusion injury, and brain parenchyma injury via regulating cellular proliferation or apoptosis levels." (PMID 38174044, 2023). "Furthermore, IGF-1 treatment is effective to reduce adverse cardiac remodeling after cardiac ischemia/reperfusion injury, when IGF-1 is administered systemically." (PMID 33614740, 2020). "We hypothesized that IGF-1 could play a protective role in myocardial ischemia by enhancing the circulating levels of angiogenic factors." (PMID 21651821, 2011). "Myocardial ischemia arising from ISO treatment significantly increased (p < 0.05) heart weight of rats when compared with corresponding measurements in both the treated only with IGF-1 and control rats." (PMID 21651821, 2011). "We hypothesize that IGF-1 could play a protective role in myocardial ischemia by enhancing the circulating levels of angiogenic cytokine interleukin-8." (PMID 22272091, 2011). "The aim of the present research was to determine whether a short term administration of IGF-1 had an effect on circulating angiogenic factors following myocardial ischemia in rats." (PMID 21651821, 2011). "Furthermore, according to previous studies, IGF1 promotes heart survival, which may accelerate protein metabolism, promotes cardiomyocyte growth, and regulates myocardial contraction, while inhibiting apoptosis during cardiac ischemia." (PMID 32880387, 2020). "During cardiac ischemia, a series of vascular cytokines, such as VEGF, fibroblast growth factor beta (βFGF), Insulin-like growth factor (IGF-1), Platelet Derived Growth Factors (PDGF), and angiopoietin are required to activate vascular reparative pathways." (PMID 28448588, 2017). "These responses in VEGF and TGF-ß levels were further elevated in rats treated with both IGF-1 and ISO, the latter inducing myocardial ischemia." (PMID 21651821, 2011).
skin cancer (17 papers, 2008 to 2026). "Elevated IGF-1 levels were linked to prostate, breast, and skin cancer outcomes, but were linked to lower hazard across most other diseases." (PMID 36535980, 2022). "Exercise has been previously reported to lower cancer risk through reducing circulating IGF-1 and IGF-1-dependent signaling in a mouse skin cancer model." (PMID 27509024, 2016). "In ordinary mice treated with carcinogens, rosiglitazone does not reduce skin cancer risk, but rosiglitazone does reduce skin cancer risk in transgenic mice overexpressing IGF1." (PMID 25655946, 2015). "IGF-1 directly influences the risk of D04 Carcinoma in situ of the skin." (PMID 38487847, 2024). "As a function, IGF-1 has been shown to stimulate proliferation of keratocytes, fibroblasts, and other skin cells, which could influence skin cancer risk." (PMID 36066621, 2023). "Given this new paradigm of photocarcinogenesis involving dermal fibroblast senescence with resultant IGF-1 deficiency, therapeutics designed to prevent or treat fibroblast senesce could have use, especially in populations at high risk for skin cancer." (PMID 34836359, 2021). "Our previous studies conducted in TPA-promoted mouse skin cancer model have demonstrated that the reduction of IGF-1 in response to exercise-induced weight loss corresponded to a concomitant inhibition of IGF-1-dependent mitogenic cascades and thus diminution of TPA-promoted signaling." (PMID 27509024, 2016). "A reduction in circulating levels of IGF-1 can significantly inhibit the development of skin tumors in mice." (PMID 39638246, 2024). "IGF-1 is produced by HDFs in the skin, and senescent HDFs secrete insufficient levels of IGF-1, resulting in keratinocytes becoming prone to initiating skin cancer." (PMID 33381190, 2020). "Evidence includes demonstration of the critical role for Akt in insulin like growth factor-1 (IGF-1)-mediated mouse skin tumour promotion." (PMID 28696382, 2017). "It was previously shown that inhibition of PI3Ks with the pan inhibitor LY294002 reduced chemically-induced skin tumour promotion in a mouse model overexpressing IGF1." (PMID 28696382, 2017). "Moreover, in murine models of skin cancer, regular exercise has been shown to suppress IGF-1 signaling, contributing to potential anticancer protection." (PMID 40895542, 2025). "K5.IGF-1 transgenic mice also form skin tumors with only DMBA initiation." (PMID 21297902, 2010). "However, a later study by the same group did show that rosiglitazone may reduce the occurrence of skin cancer in transgenic mice overexpressing insulin-like growth factor 1 (IGF1)." (PMID 25655946, 2015). "Elevated PI3K/AKT activity and subsequent activation of one or more downstream effector pathways contributed significantly to the tumor-promoting action of IGF-1 in the epidermis of BK5 (Keratin 5, derived from epithelial cells), a skin cancer model." (PMID 39638246, 2024). "Our previous studies conducted in a mouse skin cancer model demonstrated a down-regulation of IGF-1 and IGF-1 signaling pathways was an essential cancer preventive target by exercise." (PMID 27509024, 2016). "Overexpression of IGF-1 in the keratin 5 (K5) positive epidermal basal cells activates IGF-1R signaling, which promotes downstream mitogenic and cell survival signaling, resulting in spontaneous skin tumor formation." (PMID 35401828, 2022). "Our group has determined that the lack of IGF-1 expression due to fibroblast senescence in the dermis of geriatric individuals is correlated with an increased incidence of skin cancer." (PMID 34836359, 2021).
skin cancer (continued). "Yu and collaborators tested a 20 m/min, 60 min/day and 5 days/week for 10 weeks protocol in mouse skin cancer model and found that exercised mice showed reduced IGF-1 bioavailability via IGFBP-3 augmented expression and IGF-1 downregulation via PTEN (a tumour suppressor gene) overexpression." (PMID 33371214, 2020). "Transgenic mice that overexpress IGF-1 in the epidermis via either a K1 or K5 promoter are hypersensitive to the proliferative effects of TPA and develop skin tumors without carcinogen initiation." (PMID 21297902, 2010).
thyroid (17 papers, 2010 to 2025). "Nevertheless, excessive thyroid hormones can repress the secretion of pituitary growth hormone and reduce the levels of IGF-1 (Insulin-like growth factor-1), which contributes to influencing muscle mass and function as reflected by mediating muscle growth and regeneration." (PMID 38501102, 2024). "IR may also overstimulate insulin-like growth factor-1, -2, and insulin receptors, which contribute to thyroid carcinogenesis." (PMID 36077642, 2022). "Similarly, multiple signaling pathways, such as IGF-1, STAT3, and Shh, play a role in regulating thyroid CSC growth." (PMID 26973599, 2016). "Our findings are consistent with signaling or response to thyroid or non-thyroid hormones (including IGF-1 signaling), neuronal protection, angiogenesis and ciliogenesis influencing TSH levels and thyroid diseases." (PMID 37872160, 2023).
Adrenal insufficiency (16 papers, 2013 to 2026). Insufficient production of steroid hormones (primarily cortisol) by the adrenal glands. "Adrenal insufficiency and growth hormone deficiency were excluded via normal cortisol and IGF-1 levels." (PMID 41585808, 2025). "Although thyroid function was normal, low IGF-1 levels suggested secondary adrenal insufficiency." (PMID 39552964, 2024). "In the presence of secondary adrenal insufficiency, a pituitary RMI with contrast agent (unless contraindicated) and tests of the other hormone axes (FSH, LH, FT4, TSH, prolactin, testosterone in males and estradiol in females, IGF-1) are recommended." (PMID 35407442, 2022).
congestive heart failure (16 papers, 2015 to 2025). Failure of the heart to pump a sufficient amount of blood to meet the needs of the body tissues, resulting in tissue congestion and edema. "In a rat model of chronic heart failure, ghrelin elevated blood levels of GH and IGF-1 and improved cardiac function." (PMID 36009817, 2022). "Alternatively, exposure of c-kit (+) cells to exogenous IGF-1 before engraftment may represent a promising approach in patients with chronic heart failure." (PMID 27488808, 2016).
deficiencies (16 papers, 2008 to 2024). "IGF-1 (mecasermin) and GH treatments both enhance growth in children with deficiencies, but they operate through different mechanisms and have distinct efficacy and side effect profiles." (PMID 39529965, 2024). "Epidemiological data are consistent with the concept that congenital IGF1 deficiency, or deficiency in early childhood, confers protection against future development of cancer." (PMID 33182502, 2020). "Other situations leading to congenital IGF1 deficiency are post-GH-R signaling anomalies (e.g., STAT5 defects), acid labile subunit (ALS) mutations, and the recently described mutation in the PPA2 protein." (PMID 31208077, 2019). "Of importance is the fact that immune deficiency has been reported in association with congenital IGF1 deficiencies." (PMID 31208077, 2019). "Using the iLID model, we induced IGF-1 deficiency after the critical phase of growth and development and followed the mice up to two years of age." (PMID 24341939, 2014). "LS may also be caused by post-receptor pathways defects, and it leads to congenital IGF1 deficiency." (PMID 31208077, 2019). "However, it is unlikely that the effects of ghrelin on bone are exclusively mediated through a GH/IGF-1 axis since ghrelin administration increases bone mass in genetically GH-deficient rats." (PMID 25866509, 2015). "Moreover, IGF-1 levels could provide evidence for the presence of GH deficiencies." (PMID 33327247, 2020). "Given the important role of IGFBPs in modulation of IGF1/IGF2 action, we investigated the impact of congenital IGF1 deficiency on IGFBPs expression." (PMID 33182502, 2020). "In GH-deficient (GHD) patients, who exhibit major reductions in serum IGF-1, there is significantly impairment of natural killer (NK) cell activity, both unstimulated and stimulated by INFγ or IL-2." (PMID 24341939, 2014). "Leptin has been shown to regulate GH secretion and serum leptin levels have been associated with circulating IGF-1 and IGFBP-3 levels in normal and GH-deficient humans." (PMID 19017403, 2008). "Of notice, congenital IGF1 deficiencies were reported not to be associated with immune deficiency." (PMID 33182502, 2020). "The coupling of NO and IGF-1 metabolic and signaling pathways might highlight early markers, such as the inhibition of NOS measured as a lower Arg/ADMA ratio in our CF patients, for growth hormone deficiencies and nutritional failure." (PMID 32604946, 2020). "Assessment of GH secretion through quantification of IGF-1 only may be inconsistent, since the isolated quantification of this hormone does not have diagnostic value for GH deficiencies in adults; however, it may be useful for long-term follow-up." (PMID 30542321, 2018).
fibromyalgia (16 papers, 2007 to 2025). A chronic disorder of unknown etiology characterized by pain, stiffness, and tenderness in the muscles of neck, shoulders, back, hips, arms, and legs. "Reportedly, fibromyalgia (FM) is frequently associated with reduced IGF-1 levels and GH hyporesponsiveness to different GH stimulation tests." (PMID 28744309, 2017). "There is some evidence of functional GH deficiency, expressed as low insulin-like growth factor 1 (IGF-1) serum levels, in a subset of fibromyalgia patients." (PMID 18053120, 2007). "Low GH and IGF-1 levels are associated with pain hypersensitivity, and GH therapy may benefit patients with fibromyalgia or chronic lower back pain." (PMID 40003638, 2025). "Sustained augmentation of IGF-1 with the test supplement may represent a novel method of improving clinical symptoms, including stress-related weight gain, in individuals with fibromyalgia and stress-associated low-normal hGH." (PMID 36998474, 2023). "Studies in fibromyalgia show relative GH deficiency and low or low-normal IGF-1 levels." (PMID 33585528, 2021). "Treatment with a low dose of rhGH for up to 12 months resulted in an increase in IGF-1 and improvement in fibromyalgia impact scores." (PMID 36998474, 2023). "In individuals with suboptimal control of fibromyalgia and low-normal IGF-1 levels, the supplement resulted in an increase in IGF-1 levels from baseline." (PMID 36998474, 2023). "One study examined the effect of treatment with a low dose of rhGH on fibromyalgia outcomes in women with fibromyalgia and low to moderate hGH levels (defined as IGF-1 levels below 150 ng/mL at baseline)." (PMID 36998474, 2023). "A previous study also reported a positive correlation between the BMD and IGF-1 levels in the lumbar (L1–4) and trochanteric regions of patients with fibromyalgia syndrome (FMS)." (PMID 22951396, 2012). "There is evidence of functional growth hormone (GH) deficiency, expressed by means of low insulin-like growth factor 1 (IGF-1) serum levels, in a subset of fibromyalgia patients." (PMID 18053120, 2007). "The present findings indicate the advantage of adding a daily GH dose to the standard therapy in a subset of severe fibromyalgia patients with low IGF-1 serum levels." (PMID 18053120, 2007). "Futhermore, serum GH together with normal/low IGF-1 levels have been found elevated fibromyalgia syndrome, suggesting a GH resistance, and mediating a pro-inflammatory state responsible in part for the pain suffered by these patients." (PMID 18053120, 2007). "Currently in fibromyalgia patients with low IGF-1 serum levels, the administration of r-hGH demonstrated efficacy as compared with placebo in a randomized, double-blind study." (PMID 18053120, 2007). "We investigated the efficacy and safety of low dose GH as an adjunct to standard therapy in the treatment of severe, prolonged and well-treated fibromyalgia patients with low IGF-1 levels." (PMID 18053120, 2007). "The present study suggests the advantage of adding a 0.0125 mg/Kg r-hGH daily dose to the standard therapy versus the standard therapy alone in a subset of severe fibromyalgia patients with low IGF-1 serum levels." (PMID 18053120, 2007). "Regarding fibromyalgia patients with low IGF-1 levels, GH administration demonstrated efficacy and a good tolerability profile in a placebo-controlled study." (PMID 18053120, 2007). "Although other studies allowed the presence of other medications, no clinical trials have been conducted with GH as an adjuvant agent added to homogeneous active treatment in the management of severe and prolonged fibromyalgia with low IGF-1 levels so far." (PMID 18053120, 2007). "Briefly, a lack of correlation has been found between depressive symptoms and IGF-1 levels in fibromyalgia, osteoarthritis, patients in hemodialysis, with cerebral palsy, in people suffering from unexpected sudden loss, and with eating disorders such as anorexia or bulimia." (PMID 40141202, 2025).
fibromyalgia (continued). "We hypothesized that oral administration of the supplement for 24 weeks would increase IGF-1 levels and improve clinical symptoms in individuals with treatment-resistant fibromyalgia and low-normal IGF-1." (PMID 36998474, 2023). "Low levels of hGH and IGF-1 are well documented in individuals with fibromyalgia." (PMID 36998474, 2023). "The study enrolled 84 fibromyalgia patients with low-normal age-adjusted IGF-1 serum levels." (PMID 36998474, 2023). "Thus, our results are consistent with previous beneficial reports of the effects of hGH replacement in individuals with fibromyalgia and low IGF-1." (PMID 36998474, 2023). "Increased Serum insulin-like growth factor-1 (S-IGF-1) has been noted after physical activity in healthy subjects, while the acute release of S-IGF-1 in relation to exercise has not previously been studied in women with fibromyalgia (FM)." (PMID 28122522, 2017).